SLC7A11 (solute carrier family 7 member 11)
Diseases named in the same sentence as SLC7A11 in open-access papers (continued):
Sharing a sentence is not in itself a finding about the gene and the disease.
cancer (continued). "In recent years, SLC7A11 has emerged as a promising therapeutic target in cancer therapy." (PMID 33000412, 2021). "On the one hand SLC7A11 overexpression promotes cancer progression by suppressing ferroptosis." (PMID 34761566, 2021). "Notably, overexpression of the cancer-stem-cell-marker CD44 enhanced the stability of SLC7A11 by promoting the interaction between SLC7A11 and OTUB1; the depletion of CD44 partially abrogated this interaction." (PMID 33540700, 2021). "A study showed that the cystine/glutamate antiporter SLC7A11 (commonly known as XCT), which is overexpressed in a variety of human cancers, could be used for GSH biosynthesis and antioxidant defense." (PMID 34123855, 2021). "Specifically, anti-PD-L1 antibodies stimulate CD8+ T cells to release cytokine IFNγ to activate the JAK-STAT1 pathway in cancer cells, thereby reducing the expressions of SLC7A11 and SLC3A2, and ultimately increasing the sensitivity of cancer cells to ferroptosis." (PMID 34796174, 2021). "However, the correlation of SLC7A11 with miR-489-3p in regulating cancer development is still unclear." (PMID 34177591, 2021). "Several studies have focused on the interaction between NRF2 and xCT, which is a transmembrane antiporter coded by the SLC7A11 gene, which is increased in several cancers and has been known to mediate the extrusion of glutamate and support the redox homeostasis." (PMID 33922165, 2021). "Importantly, recent studies also revealed that common cancer therapies, such as immunotherapy and radiotherapy, can induce ferroptosis partly through modulating SLC7A11 expression." (PMID 33000412, 2021). "Therefore, targeting SLC7A11 exhibits good potential for the treatment of cancer, and several drugs targeting SLC7A11 are being prepared for clinical testing." (PMID 34568075, 2021). "Therefore, TalaA is a potential drug candidate that can not only take advantage of the high ROS level to kill cancer cells, but also provides targeted therapy for cancer types with high expression of anti-oxidation molecules such as SLC7A11." (PMID 33203867, 2020). "This review discusses the roles of SLC7A11 in regulating the antioxidant response and nutrient dependency of cancer cells, explores our current understanding of SLC7A11 regulation in cancer metabolism, and highlights key open questions for future studies in this emerging research area." (PMID 29764521, 2018). "Both studies proposed that, because SLC7A11 exports large amounts of intracellular glutamate in exchange for extracellular cystine, cancer cells with high SLC7A11 expression have more limited metabolic flexibility and are more dependent on glucose for survival." (PMID 29764521, 2018). "A deeper understanding of SLC7A11 in cancer metabolism may identify new therapeutic opportunities to target this important amino acid transporter for cancer treatment." (PMID 29764521, 2018). "Notably, recent studies have highlighted the emerging roles of SLC7A11 in regulating nutrient dependency of cancer cells." (PMID 29764521, 2018). "In addition, SLC7A11 overexpression renders cancer cells more resistant to chemotherapy by temozolomide or cisplatin treatments." (PMID 29764521, 2018). "These correlations suggest that Nrf2 supports SLC7A11 expression in a subset of cancer cells." (PMID 28429737, 2017). "Indeed, we clearly demonstrate that cancer cells with high SLC7A11 levels were the least responsive to system xC− inhibition." (PMID 28348409, 2017). "Moreover, Nrf2 target gene expression shows high correlation with SLC7A11 expression across 947 cancer cell lines." (PMID 28429737, 2017).
cancer (continued). "Given that xCT/SLC7A11 expression correlates with the ability of cystine to induce glutamine anaplerosis, we reasoned that xCT/SLC7A11 expression might also be a determinant of glutaminase dependence in cancer cells." (PMID 28826492, 2017). "Apart from dysfunctional metabolism of dicarboxylates, tyrosine degradation, initiated by the tyrosine transamination with 2-oxoglutarate, and glutamate exchange for cystine through xc− cystine/glutamate antiporter SLC7A11, are considered important for cancer cell metabolism." (PMID 27027236, 2016). "Small interfering SLC7A11 RNA increased sensitivity to various agents in cancer cell lines." (PMID 25622337, 2015). "From our RNA (over)expression data we also note that SLC7A11 protects against oxidative stress; extrapolating the gene expression data into their interactomes brings the numerous pro-cancer signaling pathways into view along with their relationships to chemoresistance." (PMID 24039668, 2013). "Therefore, IHC staining was used to detect the SLC7A11 expression of 5 common cancer types." (PMID 40083702, 2025). "Other ferroptosis inducers with clinical trial include Imidazole Ketone Erastin (IKE), which functions in inhibiting the SLC7A11, has been shown to play an important role in the treatment of ferroptosis in some cancers, future studies could examine this as a possible target of EC ferroptosis." (PMID 40855044, 2025). "Finally, we systematically review recent developments in SLC7A11-targeted cancer therapy." (PMID 39569390, 2025). "However, recently, Gan's group proposed a new perspective that cancer cells expressing high levels of SLC7A11 may be unfavorable for their survival in a glucose starvation or glutamine starvation condition." (PMID 39569390, 2025). "The activation of cellular glucose metabolism by the MYC oncoprotein has been shown to enhance the production of NADPH, which may serve as a reducing agent to facilitate the resolution of disulfide bonds, thus suppressing disulfidptosis in cancer cells characterized by high levels of SLC7A11." (PMID 41343099, 2025). "However, a recent study reported that a high level of SLC7A11 may deplete the redox system of cancer cells, especially in glucose-starvation conditions, which could be detrimental to cancer cells." (PMID 39569390, 2025). "This suggests that the regulatory mechanism for SLC7A11 may be cell and cancer type dependent." (PMID 39800682, 2025). "Additionally, exploring the mechanistic pathways through which SLC7A11 mediates these effects could provide deeper insights into its role in cancer biology." (PMID 40919148, 2025). "The ablation of key autophagy or lysosome-dependent cell death effectors, such as STAT3 and cathepsin B, could inhibit ferroptotic cancer cell death, whereas the knockout of SLC7A11 or GPX4 could reduce autophagy, thereby providing further protection against ferroptosis induced by Golgi stress." (PMID 41462678, 2025). "Additionally, glucose transporter protein inhibitors could effectively inhibit cellular glucose uptake, causing NADPH depletion, actin cytoskeleton cross-linking, and disulfidptosis in SLC7A11-high cancer cells." (PMID 40303412, 2025). "Furthermore, SLC7A11, which plays an essential role in cystine import for glutathione biosynthesis and antioxidant defense, is frequently overexpressed across multiple human cancers." (PMID 40610429, 2025). "However, contrary to this hypothesis, treatment with the glycolysis inhibitor 2‐deoxy‐glucose (2DG) effectively prevented glucose‐starvation‐induced cell death in SLC7A11‐high cancer cells." (PMID 39354653, 2025).
cancer (continued). "Given that upregulated SLC7A11 is common in human cancers, the discovery of disulfidptosis expands the framework of programmed cell death and may lead to new treatment and therapeutic targets for multiple cancers." (PMID 40427051, 2025). "An ROC curve showed that SLC7A11 could effectively distinguish HCC from para-cancer tissues." (PMID 39744233, 2025). "Additionally, SLC7A11 was reported to be up-regulated in several cancers." (PMID 39796103, 2024). "Furthermore, we investigated the prognostic significance of SLC7A11 across multiple cancer types." (PMID 38655266, 2024). "It was reported that inactivation of neurofibromin 2 renders cancer cells susceptible to ferroptosis through inhibiting YAP/TAZ signaling, whereas activation of epidermal growth factor receptor (EGFR) and isocitrate dehydrogenase 1 promote ferroptosis by inhibiting SLC7A11 and GPX4, respectively." (PMID 39568772, 2024). "Therefore, knockdown of SLC7A11 is proposed to make cancer cells vulnerable to ferroptosis." (PMID 39420439, 2024). "In fact, the overexpression of SLC7A11 may even suppress ferroptosis and promote cancer growth." (PMID 38674143, 2024). "Therefore, cancer cells, which are often subjected to high levels of oxidative stress, may depend on SLC7A11 to satisfy their growth requirements via cystine import." (PMID 38862581, 2024). "Moreover, the addition of α-ketoglutarate (α-KG), a metabolite derived from glutamate, effectively restored the viability of cancer cells with elevated levels of SLC7A11 during glucose deprivation, indicating a potential role for exported glutamate in promoting cancer cell death." (PMID 39040097, 2024). "Interestingly, inhibition of SLC7A11 by ferroptosis inducers sensitizes cancer cells to IR." (PMID 38705513, 2024). "In conclusion, our overall results demonstrate that FPR2 agonists and NOX modulate SLC7A11/xCT expression and activity, thereby identifying a novel regulative pathway of the cystine/glutamate antiport that represents a new potential therapeutical target for the treatment of human cancers." (PMID 38790657, 2024). "However, the mechanisms regulating SLC7A11 expression, the transporter activity, and its specific role in controlling ferroptosis in cancer cells remain unknown." (PMID 39350768, 2024). "Furthermore, research indicates that high SLC7A11 expression may correlate with cancer drug resistance." (PMID 38886311, 2024). "Overall,these discoveries provide a distinctive viewpoint on the function of SLC7A11 across different diseases, emphasizing the need to consider the impacts of mentioned drug resistance or radiation resistance when aiming to implement disulfidptosis in certain cancers." (PMID 38739940, 2024). "Furthermore, sonosynthetic oxygenation suppresses the expression of hypoxia‐inducible factor 1α, leading to reduced stability of downstream SLC7A11 mRNA, which results in glutathione depletion and inactivation of glutathione peroxidase 4, thereby inducing ferroptosis of cancer cells." (PMID 38867396, 2024). "In addition, cystine/glutamate antiporter xCT (SLC7A11) may be involved in this mechanism, because 4F2hc regulates the stability and transport activity of it in cancer cells." (PMID 38561668, 2024). "In this context, the observation that FPR2 agonists and NOX modulate SLC7A11/xCT expression and activity provides alternative possibilities to control the cystine/glutamate antiport and thus to develop new therapeutical strategies for the treatment of human cancers." (PMID 38790657, 2024). "Thus, ferroptosis is a targetable vulnerability of cancer, and targeting ferroptosis by suppressing the SLC7A11-GSH-GPX4 axis may provide new therapeutic methods for treating different cancers." (PMID 38378601, 2024).
cancer (continued). "Furthermore, SSZ is currently being explored therapeutically as a treatment in patients with cancer, though this is based on its ability to reduce pain via efflux of glutamate due to its inhibitory effect on the cysteine/glutamate antiporter SLC7A11 (Clinical Trial NCT number NCT03847311)." (PMID 37575281, 2023). "Additionally, they used data mining to thoroughly investigate whether SLC7A11 overexpression is connected to how well immunotherapy works for cancer patients." (PMID 37238995, 2023). "Further mechanistic investigations demonstrate that this vulnerability in cancer cells lacking ARID1D results from low basal levels of GSH due to reduced expression of SLC7A11 caused by impaired ARID1A-mediated chromatin remodeling and transcriptional activation." (PMID 36980292, 2023). "Notably, accumulating studies have indicated SLC7A11 as a ferroptosis suppressive gene that may be overexpressed in many human cancers." (PMID 37280673, 2023). "We hypothesized that SLC7A11 might be up-regulated in response to selenite challenge and, therefore, combining selenite with glucose starvation could achieve synergistic induction of oxidative stress and cytotoxic effect on cancer cells." (PMID 35053507, 2022). "Additionally, glucose deprivation was observed to induce SLC7A11 expression in cancer cells." (PMID 35280777, 2022). "Moreover, using the same single-cell RNA-seq dataset, we evaluated SLC7A11-positive macrophages in other cancer types with SPP1-positive macrophages, a poor prognostic factor based on previous studies, because Spp1 was also detected in our 26 commonly upregulated genes." (PMID 36470862, 2022). "Therefore, targeting SLC7A11 may be a promising therapeutic strategy to selectively treat cancer with minimal effects on normal tissues." (PMID 36552652, 2022). "Therefore, this review intends to understand the role of cysteine in antioxidant and redox signaling, the regulators of cysteine bioavailability in cancer, the role of SLC7A11 linking cysteine redox signaling in cancer metabolism and targeting SLC7A11 for novel cancer therapeutics." (PMID 36552652, 2022). "Cancer cells with higher SLC7A11 expression levels may be highly dependent on certain nutrients—such as glucose and glutamine—for survival, which can inform therapeutic strategies to target these cancer-specific metabolic vulnerabilities." (PMID 35804831, 2022). "Therefore, targeting SLC7A11 is an important means to induce ferroptosis for cancer therapy." (PMID 36046690, 2022). "Therefore, targeting SLC7A11 in combination with immunotherapy may work as an effective treatment strategy for certain cancers." (PMID 35280777, 2022). "While, the role of SLC7A11 in therapeutic resistance is still unclear, it could be demonstrated by numerous studies showing that SLC7A11, a cystine/glutamate antiporter, imported specific anti-cancer molecules and drugs." (PMID 35566360, 2022). "However, for cancer cells with low SLC7A11 expression, the situation is more complicated." (PMID 35804831, 2022). "Therefore, SLC7A11 inhibition or cystine removal in the culture medium could significantly provoke potent ferroptosis in many cancer cells." (PMID 35884471, 2022). "In addition, SLC7A11 was overexpressed in numerous cancers and is correlated with poor survival." (PMID 36133439, 2022). "Ferroptosis is triggered by lipid peroxidation and is tightly regulated by SLC7A11, a key component of the cystine-glutamate antiporter, and thus, exploring its regulatory mechanism is helpful in finding further novel therapeutic targets for inducing ferroptosis in cancer therapy." (PMID 34162423, 2021).
cancer (continued). "Finally, we will discuss how our understanding of SLC7A11 function in ferroptosis and nutrient dependency informs strategies to target SLC7A11 in cancer and highlight important unknown questions for future investigation." (PMID 33000412, 2021). "Hence, it is significant to investigate the role of SLC7A11 in cancer development." (PMID 34938318, 2021). "Therefore, metformin inhibits SLC7A11 expression in a posttranscriptional manner and may play its anti-cancer role by inhibiting the SLC7A11 protein level." (PMID 34162423, 2021). "However, few studies systematically discussed the prognostic role of SLC7A11 in cancers." (PMID 34938318, 2021). "Interestingly, the landscape of SLC7A11 expression across cancers changed dramatically." (PMID 34938318, 2021). "In line with this, it was shown that cancer cells with KEAP1 mutation and/or NRF2 hyperactivation exhibit increased glutamine dependency and enhanced sensitivity to glutamine deprivation or glutaminase inhibition, partly via high SLC7A11-mediated glutamate export in these cancer cells." (PMID 33000412, 2021). "Therefore, SLC7A11 shows great potential as a new target for cancer therapy." (PMID 34761566, 2021). "Therefore, SLC7A11 may serve as a potential novel target for cancer therapy and may enhance radiosensitivity." (PMID 34446045, 2021). "Hence, it is significant to investigate whether there are correlations between SLC7A11 expression and patients’ potential response to immunotherapy in the pan-cancer level." (PMID 34938318, 2021). "In addition, K–M curves were used to evaluate the prognostic value in differentiation ER subtypes, which revealed that SLC7A11 specifically associated with OS in ER-positive cancers, but not in ER-negative cancers." (PMID 35252218, 2021). "Recent studies have revealed that SLC7A11 promotes cystine uptake and glutathione biosynthesis, resulting in protection from oxidative stress and ferroptotic cell death, and plays critical roles in regulating the glucose and glutamine dependency of cancer cells." (PMID 34026845, 2021). "Importantly, since GATA2 functions upstream of NR3C1 and other enzalutamide-induced cancer-promoting genes (e.g. SLC7A11 and LAMP3), targeting GATA2 maybe a better strategy for improving AR-targeted therapy by enzalutamide." (PMID 31501863, 2019). "Moreover, high levels of SLC7A11 expression have been observed in several types of cancer." (PMID 29562706, 2018). "In cancer cells, cellular GSH levels are influenced not only by upregulated xCT (SLC7A11) but also by altered glutamate transporters, particularly EAAT3." (PMID 39987248, 2025). "The blockade of SLC7A11‐mediated cystine transport using erastin leads to intracellular GSH depletion and triggers ferroptosis in numerous cancer cell types." (PMID 39354653, 2025). "The NRF2 pathway transcriptionally regulates the expression of SLC7A11 and GPX4 to inhibit ferroptosis in cancer cells." (PMID 40223081, 2025). "In the present study, significantly upregulated SLC7A11 levels were confirmed in HCC tissue and multiple types of cancers, which were related to poorer survival." (PMID 40978058, 2025). "Consistent with its protective role, ferroptosis can be triggered in drug-resistant cancer cells (e.g., cisplatin-resistant HNC cells) by inhibiting or knocking down SLC7A11." (PMID 40535769, 2025). "In cancer cells, dysregulated expression of the cysteine transporter SLC7A11 (Solute Carrier Family 7 Member 11) imports cystine, biosynthesis GSH, thereby inhibiting ferroptosis." (PMID 40538852, 2025). "Transcriptomic analyses across cancers demonstrate strong correlations between GSH, SLC7A11, PKM2, glycolysis, and ferroptosis pathways." (PMID 41215470, 2025). "Many small molecular drugs such as eRAStin (SLC7A11 inhibitor) and RSL3 (GPX4 inhibitor) can specifically induce ferroptosis, especially for cancer cells carrying mutant ras oncogene." (PMID 40535125, 2025).